AKAP12 (A-kinase anchoring protein 12)
Diseases named in the same sentence as AKAP12 in open-access papers (continued):
Sharing a sentence is not in itself a finding about the gene and the disease.
meningioma (continued). "Recently, a team from Fujian Medical University found that MEG3 mediated meningioma cell cycle arrest through miR-29c/A-kinase anchoring protein 12 (AKAP12) axis and inhibited tumor cell migration, invasion, and proliferation; thus, providing a new biomarker for the treatment of meningioma." (PMID 36544907, 2022). "We sought to determine whether the increased malignancy and decreased expression of AKAP12 in high-grade meningiomas and sh33-AKAP12 cells were connected through kinase regulation." (PMID 29391485, 2018). "Upregulation of ERK1/2 T202/Y204 and downregulation of STAT3 mediated by AKAP12 may be resulting in the overexpression of CCND1 in high-grade meningiomas." (PMID 29391485, 2018). "Finally, low levels of AKAP12 in an independent cohort was indicative of high-grade, invasive, and recurrent/progressed meningiomas, demonstrating the AKAP12 as a prognosis biomarker." (PMID 29391485, 2018). "The frequent and discordant increase in kinase activity in atypical meningiomas also suggests that AKAP12 may regulate kinase activity through mechanisms unique to grade III tumors." (PMID 29391485, 2018). "After AKAP12 silencing, the benign SF4433 cells acquired a similar proteomic profile to anaplastic meningiomas, suggesting that AKAP12 may play a role in meningioma progression." (PMID 29391485, 2018). "To determine how AKAP12 and meningioma grade influence global signaling we employed Ingenuity Pathway Analysis (IPA) of STK peptide array (sh33-AKAP12: sh33NS) and the grade II:I and III:I phosphoproteome/kinome combined datasets (iTRAQ LC MS/MS and STK peptide array)." (PMID 29391485, 2018). "By contrast, the lack of congruence between phosphorylation states (hyper- or hypophosphorylated) of peptides in grade II and sh33-AKAP12 cells suggests that in grade II meningiomas AKAP12 is influencing shared pathways through upregulating rather than inhibiting kinase activity." (PMID 29391485, 2018). "RHOA-ROCK-LIMK kinase activation was seen after AKAP12 knockdown indicating that AKAP12 may regulate RHOA-ROCK-LIMK pathway in grade II meningiomas." (PMID 29391485, 2018). "To understand whether AKAP12 function is associated with regulation of specific kinase pathways we first assessed the overlap of differentially phosphorylated peptides found in grade II and III meningiomas versus grade I and those differentially regulated by AKAP12 knockdown." (PMID 29391485, 2018). "For example, the invasiveness and aggressiveness of meningiomas were related to an upregulation of MMP-9 and a downregulation of E-cadherin, AKAP-12, and DEP-1." (PMID 36077700, 2022). "We suggest that low AKAP12 disrupts PKA scaffolding, inactivating downstream signaling, resulting in uncontrolled migration and invasion in aggressive meningiomas." (PMID 29391485, 2018). "AKAP12 seems to downregulate the AKT pathway by inactivating PDK1 Ser241, and IKKα Thr23 in meningiomas." (PMID 29391485, 2018). "Since AKAP12 downregulation may fail to scaffold PKA resulting in the inhibition of the PKA cascade, it activates ERK1/2 through direct PKC activation and leads to enhanced cellular migration in high-grade meningiomas." (PMID 29391485, 2018). "Another meningioma series reports significant upregulation of AKAP12 and phospho-AKAP12 in Grade I and II meningiomas compared to meningeal tissue, while a non-significant increase is reported for Grade III meningiomas; in any case, the involvement of AKAP12 seems warranted." (PMID 31671850, 2019).
colorectal cancer (9 papers, 2011 to 2024). A primary or metastatic malignant neoplasm that affects the colon or rectum. "Complete loss of AKAP12 and hypermethylation of the promoter was detected in colorectal cancer cell lines, LoVo, SW480 and COLO320." (PMID 21918680, 2011). "Our recent study demonstrated the highly recurrent loss of AKAP12 in colorectal cancer and AKAP12 reexpression inhibited proliferation and anchorage-independent growth in colorectal cancer cells, implicating AKAP12 in colorectal cancer pathogenesis." (PMID 21918680, 2011). "In our previous study, downregulation or loss of AKAP12 mRNA expression was detected in 68.9% (31/45) of colorectal carcinoma tissues and methylation of the AKAP12 promoter region was detected in 77.8% (35/45) of these tissues compared with 13.3% (6/45) in the adjacent tissue." (PMID 21918680, 2011). "In recent years, a series of studies have reported that AKAP12 expression is downregulated in many types of tumors, such as liver cancer, colorectal cancer, prostate cancer, and lung cancer." (PMID 36148016, 2022). "It has been shown that AKAP12 mRNA was under-expressed in 31 out of 45 (69%) colorectal carcinoma tissues and methylation of AKAP12 promoter region was detected in 35 (78%) of these tissues." (PMID 25527095, 2015). "Studies have shown that AKAP12 is a tumor suppressor and reexpression of AKAP12 inhibits progression and metastasis of colorectal carcinoma." (PMID 25180175, 2014). "To examine the impact of the AKAP12 re-expression in colorectal cancer cells, we constructed a vector constitutively expressing AKAP12 (pCMV6-AKAP12) to restore AKAP12 expression in LoVo cells, which lack AKAP12 expression in our previous study." (PMID 21918680, 2011). "The upregulation of AKAP12 is related to poor survival of colorectal cancer." (PMID 34950205, 2021). "The re-expression of AKAP12 in LoVo cells reduced colony formation and inhibited anchorage-independent growth ability, which may explain the contribution of AKAP12 to colorectal cancer progression." (PMID 21918680, 2011). "To examine whether modulation of AKAP12 expression influenced the tumorigenic properties of the colorectal cancer cells, we tested in vitro LoVo cell proliferation and apoptosis." (PMID 21918680, 2011). "AKAP12 also could inhibit colorectal cancer tumorgenesis and metastasis in vivo and suggests that AKAP12 may hold great promise for designing novel therapeutic strategies against this solid cancer." (PMID 21918680, 2011). "The biological role of AKAP12 in colorectal cancer progression and metastasis is poorly understood." (PMID 21918680, 2011). "In agreement with this hypothesis, our results demonstrated that, in vitro, induced expression of AKAP12 could reduce the invasion or migration ability of oncogenic cells and significantly suppress the metastatic potential of the colorectal cancer cells." (PMID 21918680, 2011). "Our data demonstrate that the re-expression of AKAP12 could inhibit the progression and metastatic potential of colorectal carcinoma." (PMID 21918680, 2011). "Therefore, AKAP12 could serve as an effective target for the development of novel anti-cancer therapies and may be a useful biomarker for human colorectal cancer." (PMID 21918680, 2011). "However, it remains unclear if AKAP12 plays an inhibitory role in the progression or metastasis of colorectal cancer." (PMID 21918680, 2011). "We found that AKAP12 was upregulated in anti-VEGF therapy-resistant cancers, including ovarian cancer (OV), glioblastoma (GBM), lung cancer, and colorectal cancer (CRC)." (PMID 36110213, 2022). "Furthermore, injection of LoVo-AKAP12, LoVo-CON or LoVo-LIPO cells into nude mice demonstrated that, in vivo, induced AKAP12 expression in the colorectal cancer cells suppressed both tumor growth and metastasis and induced apoptosis." (PMID 21918680, 2011).
colorectal cancer (continued). "To evaluate the effect of this gene on the progression and metastasis of colorectal cancer, we examined the impact of overexpressing AKAP12 in the AKAP12-negative human colorectal cancer cell line LoVo, the single clone (LoVo-AKAP12) compared to mock-transfected cells (LoVo-CON)." (PMID 21918680, 2011). "However, in this study single clone data of a single cell line may be could not describe the exact role of AKAP12 in the progression of colorectal cancer and needs further exploration." (PMID 21918680, 2011).
gastric cancer (8 papers, 2006 to 2026). A primary or metastatic malignant neoplasm involving the stomach. "Downregulation of AKAP12 expression has been reported to cause abnormal cell cycle regulation, leading to pulmonary adenocarcinoma, prostatic hyperplasia, myelodysplastic syndrome, and gastric carcinoma." (PMID 26202611, 2015). "In human gastric cancer cells, re-expression of AKAP12 lead to reduced colony formation and apoptotic cell death." (PMID 21918680, 2011). "SSeCKS/Gravin/AKAP12 expression is severely downregulated in human prostate, breast and gastric cancer, partially relating to the mapping of the human gene to 6q24-25.1, a cancer deletion hotspot." (PMID 16638134, 2006). "Furthermore, the reexpression of AKAP12 in gastric cancer cell line induced apoptotic cell death and reduced colony formation, indicating AKAP12 is a potential tumor suppressor of gastric cancer." (PMID 36148016, 2022). "Taken together, we speculate that AKAP12 may also play an important role in gastric cancer tumor immunity through these immune-related pathways." (PMID 36148016, 2022). "DNA hypermethylation in the AKAP12 promoter region, and the accompanied underexpression of the corresponding gene, has been noted in a variety of human cancers, including gastric cancer, esophageal cancer and lung cancer, and in myeloma cells and myeloid malignancies." (PMID 21918680, 2011). "Moreover, CpG island hypermethylation was frequently observed in the promoter region of AKAP12 in gastric cancer, and the expression of AKAP12 can be restored through methyltransferase inhibitor, suggesting DNA methylation is directly involved in the silencing of the AKAP12 in gastric cancer." (PMID 36148016, 2022). "Gastric cancer tissues had reduced CD3+T, CD3+CD4+T cells and M1 macrophage infiltration, increased M2 macrophages and CD14+monocytes; AKAP12 was positively correlated with monocytes." (PMID 41798945, 2026).
lung carcinoma (8 papers, 2015 to 2024). "Five of the seven genes (BIRC5, GIMAP5, HBB, IL33, and AKAP12) associated with the LC-LK alignments have been observed to be deregulated in lung cancer." (PMID 36101460, 2022). "As scaffolding proteins are involved in the spatiotemporal regulation of signaling pathways the present study evidences caveolin-1 and Akap12 (gravin) to be regulated in lung cancer." (PMID 29254206, 2017). "In this context, it is worthwhile to mention that we have shown recently that cigarette smoke, a major cause not only for lung cancer but also for chronic obstructive pulmonary disease (COPD), provoked a decrease of AKAP12 and an increase of Ezrin expression in airway smooth muscle." (PMID 26202611, 2015). "Higher AKAP12 expression indicates a higher likelihood of anti-VEGF therapy resistance in cancers, especially in OV and lung cancer." (PMID 36110213, 2022). "Notably, a significant positive relationship was observed between AKAP12 and IC50 values of sorafenib in lung cancer, primary pan-cancer, and metastasis pan-cancer." (PMID 36110213, 2022).
melanoma (7 papers, 2017 to 2023). A malignant, usually aggressive tumor composed of atypical, neoplastic melanocytes. "Studies have found that hypoxia can induce the expression of scaffold protein AKAP12 in melanoma, and PKA-regulated phosphorylation during hypoxia is dependent on the presence of AKAP12." (PMID 33292604, 2020). "Inactivation of AKAP12 leading to the reduction of tumor growth, migration, and invasion in melanoma mouse models." (PMID 33292604, 2020). "Taken together, these data indicate that SSeCKS/AKAP12 suppresses melanoma adhesion to endothelial cells based on reduction of E-Selectin expression." (PMID 30323895, 2018). "We excluded the following genes that were methylated and deleted in melanoma: PTEN, BRIMS1, FERMT3 (KIND3), AKAP12 (SSeCKS), CDKN2A, APAF-1, MTAP and MEN1." (PMID 34639015, 2021). "Increased binding of melanoma cells to HUVEC and HMVEC-L cells was similarly facilitated by AKAP12 knockdown." (PMID 30323895, 2018). "Here, we analyze roles for the SSeCKS/AKAP12 metastasis suppressor in resident endothelial cells and fibroblasts that control metastatic colonization of melanoma cells in the lung, using syngeneic BrafWT and BrafC600E melanomas in immunocompetent WT or SSeCKS-null (KO) hosts." (PMID 30323895, 2018).
myasthenia gravis (7 papers, 2006 to 2024). Myasthenia gravis (MG) is a rare, clinically heterogeneous, autoimmune disorder of the neuromuscular junction characterized by fatigable weakness of voluntary muscles. "SSeCKS, originally identified as a transcriptionally-suppressed gene in v-src and ras-transformed rodent fibroblast cells, is the orthologue of human GRAVIN/AKAP12 gene that encodes a kinase-scaffolding protein that is targeted as an autoantigen in some cases of myasthenia gravis." (PMID 16638134, 2006). "A-Kinase anchoring protein 12 (AKAP12) was initially identified in patients with myasthenia gravis and was a known tumor suppressor." (PMID 34359218, 2021). "A-kinase anchor protein 12 (AKAP12/Gravin) was first isolated as a protein recognized by the serum of myasthenia gravis patients." (PMID 21918680, 2011). "AKAP12, an anchor gene that mediates the subcellular compartmentation of protein kinase A (PKA) and protein kinase C (PKC), was initially identified as a molecule associated with poor prognosis in myasthenia gravis." (PMID 36238643, 2022). "AKAP12, which is a member of the AKAP family, was originally identified in the serum of myasthenia gravis patients." (PMID 38088586, 2024). "A-kinase (PRKA) anchor protein 12 (AKAP12), also known as AKAP250, Gravin, or SSeCKS, was initially identified as a cytoplasmic antigen in sera derived from myasthenia gravis patients." (PMID 36110213, 2022). "AKAP12, originally called Gravin or AKAP250, was first recognized as an autoantigen in serum from myasthenia gravis patients." (PMID 26202611, 2015).
prostatic hyperplasia (5 papers, 2012 to 2024). "Loss of the AKAP12 results in prostatic hyperplasia and infertility in human and mice (Akakura, Huang, Nelson, Foster, & Gelman, 2008), and significantly affect feed conversion ratio in pigs (Messad, Louveau, Koffi, Gilbert, & Gondret, 2019)." (PMID 33664783, 2021). "Further, knockout of Akap12 in mice resulted in infertility, prostatic hyperplasia, and dysplastic foci and increased pAKT in vivo." (PMID 29653561, 2018). "Despite the fact that AKAP12 is widely expressed throughout embryogenesis, AKAP12-null mice (KO-mice) are viable though they exhibit spontaneous prostatic hyperplasia." (PMID 22811901, 2012). "It has been observed that Akap12 KO mice have decreased fertility along with prostate hyperplasia." (PMID 39574214, 2024). "Furthermore, knockout of AKAP12 in mice resulted in prostatic hyperplasia and dysplastic foci, supporting a role of AKAP12 as a tumor suppressor gene." (PMID 29653561, 2018).
epidermoid carcinoma (4 papers, 2010 to 2012). "In addition, we showed recently that AKAP12-null mice have increased susceptibility to papilloma and squamous cell carcinoma formation induced by DMBA and TPA, well-known skin carcinogens." (PMID 22811901, 2012). "We extended the studies from HEK293 cells to human epidermoid carcinoma A431 cells, again probing if overexpression of AKAP12 would impact the AKAP5-mediated Erk1/2 activation in response to β-adrenergic agonist." (PMID 21831305, 2011). "Interestingly, dermal layers in AKAP12-null mice are hyperplastic, and they show significant upregulation of FAK, a known promoter of carcinogen-induced squamous cell carcinoma." (PMID 22811901, 2012). "AKAR2-AKAP12 can be expressed in mammalian cells, is fully functional, and reveals the spatial-temporal activation of AKAP12 undergoing phosphorylation by PKA in response to beta-adrenergic activation in human epidermoid carcinoma A431 cells." (PMID 20412577, 2010).
ovarian carcinoma (4 papers, 2021 to 2023). A malignant neoplasm originating from the surface ovarian epithelium. "In ovarian cancer, AKAP12 has been associated with paclitaxel resistance by modulating signaling pathways related to cell survival and drug efflux." (PMID 37397367, 2023). "As researchers reported that AKAP12 serves as a tumour suppressor in various cancers such as prostate, breast and ovarian cancers." (PMID 37795791, 2023). "Elevated AKAP12 transcript expression is related to poor survival in patients with ovarian cancer and high-grade serous ovarian carcinomas." (PMID 34950205, 2021).
glioblastoma (3 papers, 2021 to 2022). The most malignant astrocytic tumor (WHO grade IV). "We also explored the correlation between the expression of PRKAR2A and other genes in glioblastoma tissue database: interestingly, PRKAR2A correlated with Golgin genes linked to vesicular membrane trafficking, and the R2-binding AKAP12." (PMID 34372567, 2021). "Paradoxically, all FGFR-fused glioblastomas shared strong PI3K and MAPK pathway suppression effected by SPRY, DUSP and AKAP12 inhibitors, whereas the FGFR2-TACC2 tumor elicited also EGFR suppression by ERRFI1 upregulation." (PMID 33853673, 2021).
heart failure (3 papers, 2018 to 2026). Inability of the heart to pump blood at an adequate rate to meet tissue metabolic requirements. "Additionally, our unpublished data indicate that AKAP12 scaffolding is crucial for isoproterenol-mediated heart failure, and loss of function of AKAP12 scaffolding can act as a treatment strategy for heart failure." (PMID 29370121, 2018). "Recurrent hypoglycaemia in the absence of diabetes was associated with changes in a small subset of genes associated with endothelial integrity, β-adrenergic signalling and heart failure, including Cldn5, Akap12, Nr4a2 and Adamts4." (PMID 41212210, 2026).
liver fibrosis (3 papers, 2019 to 2025). "Our data support a previously unidentified function of AKAP12 and its phospho-modification in regulating the outcome of liver fibrosis in animal models." (PMID 36193675, 2022). "Expression, phosphorylation, and scaffolding activity of AKAP12 is altered in CCl4-treated mouse liver and human liver fibrosis." (PMID 36193675, 2022). "Despite these differences, PMUT was effective in suppressing the fibrogenic response in the liver, supporting an important role of AKAP12 phosphorylation in regulating the outcome of liver fibrosis." (PMID 36193675, 2022). "This was associated with a 20% decrease in total AKAP12 staining and a 3.8-fold increase in HSP47 staining in liver fibrosis compared to normal." (PMID 36193675, 2022). "Our overall findings suggest a pro-fibrogenic role of AKAP12 phosphorylation that may be targeted for therapeutic intervention in liver fibrosis." (PMID 36193675, 2022). "The fact that enhanced phosphorylation of AKAP12 at its activation-responsive phospho-sites promotes HSC activation fueled our hypothesis that site-specific AKAP12 phosphorylation may be involved in promoting liver fibrosis in animal models." (PMID 36193675, 2022). "Interestingly, AKAP12 to has also been shown to play a central role in the resolution of hepatic fibrosis, raising the possibility that AKAP12 might function as an anti-fibrotic regulator in multiple organs." (PMID 31888098, 2019). "The interaction between AKAP12 and HSP47 was inhibited by 68% in human liver fibrosis tissue compared to normal." (PMID 36193675, 2022). "Since AKAP12 phospho-modification is not evident in normal HSCs but is induced upon pro-fibrogenic stimulation, AKAP12 phosphorylation may be utilized as a druggable target in liver fibrosis." (PMID 36193675, 2022). "A human liver fibrosis tissue array containing 16 liver fibrosis tissues and 11 normal tissues was stained with PLA probes for AKAP12 and HSP47 to detect their interaction." (PMID 36193675, 2022).
Stomach Adenocarcinoma (3 papers, 2022 to 2025). "Reportedly, both AKAP12 mRNA and protein levels were downregulated in patients with gastric adenocarcinoma, which might have good clinical prospects as a prognostic target." (PMID 40226362, 2025).